SBDS (SBDS ribosome maturation factor)
Diseases named in the same sentence as SBDS in open-access papers (continued):
Sharing a sentence is not in itself a finding about the gene and the disease.
tumor (continued). "For this reason, the primary objectives were to grow tumor cells in 2D and 3D tissue culture systems and to determine whether the cells grown in the culture systems and primary tumor cells had the same features of methylation in the genes PAX5, TMPRSS2, and SBDS." (PMID 30792990, 2019).
infection (2 papers, 2023 to 2024). The state of being infected such as from the introduction of a foreign agent such as serum, vaccine, antigenic substance or organism. "Intriguingly, infection of cells with IAV and Ad5, both of which were largely unaffected by loss of SBDS and SPATA5, does not cause polysome collapse or other significant changes to polysome profiles." (PMID 36809113, 2023).
SBDS also shares sentences with these, for which no sentence is quoted: exocrine pancreatic insufficiency (6 papers); Congenital neutropenia (2); growth failure (2); malignant melanoma (2); Myelodysplasia (2); cholesteryl ester storage disease (1); Cohen syndrome (1); congenital heart disease (1); cryptorchidism (1); diabetes mellitus (1); Diamond-Blackfan anemia (1); dyskeratosis congenita (1); dysplasia (1); ependymoma (1); epilepsy (1); Epileptic encephalopathy (1); genetic disorders (1); glioblastoma (1); glycogen storage disease (1); hereditary spastic paraplegia (1); Limb-girdle muscular dystrophy type 2L (1); malignant pleural mesothelioma (1); malnutrition (1); mitochondrial disease (1); Miyoshi muscular dystrophy 3 (1); osteosarcoma (1); pancreatitis (1); peripheral vascular disease (1); prostate carcinoma (1); Pseudoxanthoma elasticum (1).
A further 7 diseases each share a sentence with SBDS in 1 paper.